TNF (tumor necrosis factor)
Diseases named in the same sentence as TNF in open-access papers (continued):
Sharing a sentence is not in itself a finding about the gene and the disease.
liver fibrosis (continued). "KCs can also release pro-inflammatory cytokines, including TNF-α and IL-1β, and recruit peripheral mononuclear macrophages to the liver through the CCL2/CCR2 axis, further aggravating liver fibrosis." (PMID 39635524, 2024). "One study shows that the frequency of intrahepatic NKp44+ NK cells producing TNF-α is correlated with both HCV infection level and stage of liver fibrosis." (PMID 37239062, 2023). "An animal study indicated that increasing dietary fiber intake can effectively reduce serum pro-inflammatory factors, such as tumor necrosis factor alpha (TNF-α), interleukin (IL) 1-β, and effectively alleviate liver fibrosis." (PMID 37242277, 2023). "For instance, mouse-derived mmu-miR-92a-2-5 can target TLR2 to inhibit Schistosoma japonicum-induced liver fibrosis and downregulate the expression of TLR2-related cytokines such as IL-4, IFN-γ, and TNF-α during S. japonicum infection in mice." (PMID 37559722, 2023). "Based on the results, VSC-CDs in various dosage groups significantly diminish the levels of TNF-α, IL-6, and IL-1β, signifying that VSC-CDs inhibit the inflammatory response and thereby alleviate liver fibrosis." (PMID 38116381, 2023). "Herein, promising therapeutic approaches were aroused, such as the TNFα/TNFR1 axis blockage to prevent NAFLD progression, anti-TGF-β therapy to alleviate liver fibrosis or neutralization of IFNγ activity to revert both liver inflammation and injury." (PMID 36768637, 2023). "The potential application of mLO(-DAPT/D3) for the modeling of liver fibrosis was then examined after sustained exposure to a fibrosis-inducing cytokine cocktail (FIC, a mixture of TGFβ1, TNFα, IL-6, and IL-1β)." (PMID 36737811, 2023). "IL-6, TNF-α, MCP1, and IL-1β are the inflammatory cytokines responsible for NASH progression, which play an important role in hepatic fibrosis." (PMID 37762300, 2023). "According to a subsequent RT-qPCR study, the mRNA levels of TNFα and IL8 were significantly higher in the liver fibrosis group compared to the control group." (PMID 37091870, 2023). "Surviving Cbs knockout mice were characterized by HHCy, steatotic hepatomegaly, and early liver fibrosis with elevated levels of alanine aminotransferase (ALAT), tumor necrosis factor alpha (TNF-α), and interleukin (IL-6) in plasma." (PMID 37108182, 2023). "Taken together, TLR3 inhibit IL-6 and TNF production via p38/ERK signaling pathway, a phenomenon that resulted in the alleviation of C. sinensis-induced liver fibrosis." (PMID 37167198, 2023). "Recent studies have indicated that pro-inflammatory cytokines like TNF and IL-1β secreted by macrophages could also activate HSCs, and maintain the survival of activated HSCs through nuclear factors κB (NF-κB) signaling pathway, which aggravates liver fibrosis." (PMID 35990625, 2022). "Increased TNF and IL-17 expression, which is mediated by the NLRP3 inflammasome, is a major contributor to liver fibrosis and inflammation." (PMID 36110858, 2022). "Inflammatory cytokines, such as TNF-α, IL-6, or MCP-1, led to the induction of NFkB that accelerates the progression of liver fibrosis." (PMID 35294499, 2022). "Activation of proinflammatory cytokines and chemokines, including IL-6, IL-1β, TNFα, and MCP-1, can activate HSCs, promote ECM secretion and deposition, and then exacerbate liver fibrosis." (PMID 35525986, 2022). "Subsequently, the increase of proinflammatory mediators (i.e., TNF-α, IL-6, and IL-1β) and fibrogenesis markers (i.e., TGF-β1, α-SMA, and collagen I), as well as hepatic fibrosis in NASH stage two, were observed in the fructose group." (PMID 36359236, 2022). "After a fibrogenic stimulation, HSCs go from dormant to active Tumor necrosis factor-α (TNF-α), one of the cytokines released in inflammation that results in liver fibrosis by activating local HSCs and turning them into fibrogenic myofibroblasts." (PMID 36358524, 2022).
liver fibrosis (continued). "In liver fibrosis mice model, high selenium level elevated expression and activity of GPx and superoxide dismutase with decreasing level of MDA, TNF-α, IL-6 and MCP-1." (PMID 35975984, 2022). "Turmeric can inhibit the development of lung and liver fibrosis via its antioxidant and anti-inflammatory properties through reducing various inflammatory mediators as FOXO-3, TGF-β, TNF-α, and MCP1 in the lung and liver." (PMID 36301384, 2022). "Evodiamine was able to reduce IL-6, TNF-α, and types I and III collagen expression, inhibit the TGF-β1/Smads signaling pathway, and attenuate liver fibrosis." (PMID 35529927, 2022). "We investigated the changes in cytokines, interferon gamma (IFN-γ), tumor necrosis factor-α (TNF-α), and interleukin 6 (IL-6) along with aspartate aminotransferase (AST), alanine aminotransferase (ALT) level, and hepatic fibrosis in three regimens." (PMID 35889747, 2022). "We discovered when detecting the peripheral blood of liver fibrosis patients that the proportion of DNTs (CD3+CD4−CD8−) in peripheral blood of liver fibrosis patients significantly increased, while that of CD3+TNF-α+ also increased." (PMID 35371052, 2022). "Liver fibrosis markers, inflammatory indicator α-Fetoprotein (AFP), tumor necrosis factor-alpha (TNF-α), 25-hydroxyvitamin D, and PTH were estimated using immunoassay techniques." (PMID 33884041, 2021). "Magnesium chenoursodeoxycholic acid (Mg-CUD) suppression increases MMP-2 and tissue inhibitor of MMP-1 mRNA expression, as well as levels of NF-κB, TNF-α, IL-6, and COX-2 in carbon tetrachloride-induced liver fibrosis in rats." (PMID 34220502, 2021). "Other top-enriched KEGG pathways included TNF, NF-κB, PI3k/Akt, NOD and Toll-like receptor signaling pathways, which all play critical roles in liver fibrosis." (PMID 34765922, 2021). "The NASH group IL-12 and TNF revealed stronger and positive correlations with transient elastography parameters and NAFLD liver fibrosis score." (PMID 34447378, 2021). "As shown in the heatmap, inflammatory mediators were expressed significantly, with higher levels in the CCL4-induced liver fibrosis mice than in healthy controls (P value TLR-2 0.02, TLR-4 0.003, and TNF-α 0.03)." (PMID 34549998, 2021). "Induction of liver fibrosis in rats using TAA for 6 weeks resulted in a significant elevation in hepatic contents of IL-6 and TNF-α, as compared to the normal group." (PMID 33628797, 2021). "Foam-like KCs secrete chemokines to recruit monocytes and neutrophils and TNF-α and TGF-β to activate hepatic stellate cells, which transform them into myofibroblasts, resulting in hepatic fibrosis." (PMID 34956171, 2021). "Induction of liver fibrosis by DEN+CCl4 significantly raised liver TGF-1β expression and TNF-α content by 39.44 and 66.64%, respectively compared to the control group." (PMID 34045968, 2021). "Inflammatory cytokines such as tumor necrosis factor-α (TNF-α) worsen pathological progression, and lead to liver fibrosis that complicates the liver treatment." (PMID 34870139, 2021). "The recruited Ly6C+ MoMFs release pro-fibrotic molecules like TGF-β, TNF-α, IL-1β, PDGF and CC chemokine ligand 2, and these cytokines activate HSCs and promote liver fibrosis." (PMID 33841164, 2021). "In our study, SNS treatment reduced the serum and liver contents of TNF-α, IL-1β as well as IFN-γ in mice with liver fibrosis." (PMID 34276360, 2021). "The effect of cranberry nutraceutical (50 and 100 mg/kg) on oxidative stress markers, antioxidant enzymes, NF- κB levels in livers tissues, and serum levels of TNF-α and IL-6 in HFCD-induced liver fibrosis in rats." (PMID 32256346, 2020). "In patients with HCV-related hepatic fibrosis, NF-κB, IKKB, and TNFα mRNA and protein were highly increased." (PMID 33015132, 2020).
liver fibrosis (continued). "Currently, some researchers believe that a combination of TFAs and fructose induces oxidative stress and increases TNFα, IL-6, IL-1β and collagen-Iα expression levels, which partly explained the roles of TFA and fructose in liver fibrosis progression." (PMID 32508961, 2020). "β-Elemene decreases the levels of endotoxin in plasma, TNF-α in serum, and CD14 in the liver of rats with liver fibrosis, preventing concurrent liver fibrosis induced by carbon tetrachloride (CCl4) and reducing liver injury and inflammatory reactions." (PMID 32149121, 2020). "In this study, L02 cells (treated with TNF-α) and Lx2 cells (treated with TGF-β1) were used for simulating the HPCs apoptosis and HSCs activation in the process of liver fibrosis, respectively." (PMID 30669350, 2019). "The correlation analysis showed positive correlation between plasma endotoxin level and TNF-α level in the hepatic homogenate, and we suppose that IETM and TNF-α are two contributors for the lung pathological changes in rat models of liver fibrosis." (PMID 33817199, 2019). "Inflammatory macrophages, which promote inflammation and liver fibrosis, are activated by Toll-like receptors (TLR), with release of inflammatory (TNF, IL-1β) and pro-fibrogenic mediators (TGF-β and Gal-3) as well as chemokines (MCP-1, CCL5)." (PMID 31015492, 2019). "In this study, we successfully ameliorated liver fibrosis by blocking the function of TNF-α by etanercept-secretome, and hence, demonstrated the significant role of TNF-α in the process of liver fibrosis." (PMID 31847135, 2019). "As vigorous secretors of proinflammatory and profibrotic factors including TNF-α and TGF-β1, they drive inflammation and activate HSC thereby triggering a cascade of events leading to liver fibrosis." (PMID 29743924, 2018). "Increasing evidence indicates that inflammatory cytokines, such as TNFα, are critical to HSC activation in the pathogenesis of liver fibrosis." (PMID 30322375, 2018). "Afterward, we collected 286 targets corresponding to active ingredients in DGLHD, including TNF-α, NF-κB, AP-1, PPAR-γ, PIK3CA, and MMPs, which were involved in inflammation, cell proliferation, or ECM deposition during the development of liver fibrosis." (PMID 29556199, 2018). "The recently published sequence of key events leading to liver fibrosis involve hepatocellular injury/death, KC-activation and macrophage recruitment, TGF-β1 expression and release of cytokines (TNF-α and IL6), HSC activation, and collagen accumulation." (PMID 28665955, 2017). "Although NK cells are responsible for hepatocyte apoptosis via TNF-α TRAIL ligand, these cells have drawn attention because in certain circumstances, they act as inhibitors of hepatic fibrosis." (PMID 29176797, 2017). "We further examined the role of the endogenous IL-9 in hepatic fibrosis and its relationship with other relevant cytokines, including IL-17A, IFN-γ, TGF-β1, IL-6, IL-4, IL-21 and TNF-α in response to hepatic fibrosis, by neutralizing IL-9 in a mouse model." (PMID 26728971, 2016). "For example, plasma leptin, TNF-α and IL-6 levels positively correlate with hepatic injury and fibrosis deposition in WAT and the liver, while adiponectin attenuates hepatic fibrosis." (PMID 26891322, 2016). "Taken together, these data demonstrates that regardless the divergences in the frequency of intrahepatic T-cells, HCV patients have comparable tissue levels of proinflammatory cytokines (TNF and IFN-γ) according to their liver fibrosis score." (PMID 26742960, 2016). "The Th-1 immunity profile (IL-2, IL-12, TNF-α, and IFN-γ) is correlated with liver fibrosis in patients with chronic hepatitis C, whereas Th2 immunity profile (IL-4 and IL-10) cannot control viral clearance." (PMID 27413763, 2016). "CCl4 hepatotoxicity involves the release of TNF-α, nitric oxide, and TGF-α/β from Kupffer cells in the liver, resulting in the production of hepatic fibrosis." (PMID 27847552, 2016).
liver fibrosis (continued). "Serum levels of the inflammatory factors TNF-α and TGF-β, as well as the expression of the main liver fibrosis marker α-SMA, were also examined." (PMID 27387128, 2016). "Treatment with betulin and betulinic acid inhibited expression of TNF-α, TGF-β1, tissue inhibitor of metalloproteinase (TIMP)-1, TIMP-2, and activated matrix metalloproteinase (MMP)-2 in alcohol-induced liver fibrosis in vivo." (PMID 25897319, 2015). "The anti-liver fibrosis effect of the SPV complex is mainly due to deactivation of HSCs and downregulation of TGF-β1 and TNF-α expression." (PMID 25897319, 2015). "Taken together, BBG reduces hepatic pro-inflammatory cytokines IL-6, TNF-α, PDGF, and IL-1β expressions, down-regulates TGF-β signaling pathway, and ameliorates liver fibrosis." (PMID 25933224, 2015). "Research indicated that the serum or plasma TNF-α and IL-6 levels was higher in NASH compared healthy subjects and it was shown to correlate with liver fibrosis in advanced NAFLD." (PMID 26375281, 2015). "There is a correlation between elevated serum levels of TNF-α and an increased degree of liver fibrosis, and TNF-α generally promotes liver fibrosis." (PMID 24926330, 2014). "CBDL +CDL livers of TNF-α−/− mice showed reduced fibrosis, compared to those of TNF-α+/+ mice, suggesting that TNF-α contributes to liver fibrosis." (PMID 23755201, 2013). "Blocking tumor necrosis factor alpha (TNF-α) with antibodies has been used to successfully reduce inflammation-induced kidney and liver fibrosis, as well as collagen-induced arthritis, with subsequent improvement in symptoms." (PMID 22675458, 2012). "The usefulness of long-term anti-TNF-α treatments for WMSDS has yet to be explored, although it has been shown to reduce inflammation and scarring in experimental glomerulonephritis and hepatic fibrosis." (PMID 22675458, 2012). "In addition, cytokines including transforming growth factor-β (TGF-β), tumor necrosis factor-alpha (TNF-α) and interleukin-1β (IL-1β) promote HSCs trans-differentiation, the main source of ECM in the development of liver fibrosis 10,11." (PMID 41535693, 2026). "Rutin significantly reduces serum TNF-α, IL-17, and IL-4 in S. mansoni infection, aligning with prior studies on TFL’s suppression of Schistosoma japonicum (S. japonicum)-induced liver fibrosis." (PMID 40809521, 2025). "In conclusion, C. sinensis could cause ferroptosis, which promoted the secretions of IL-6 and TNF-α as well as the activation of TGF-β/Smad pathway, leading to exacerbated liver fibrosis." (PMID 40455823, 2025). "Increased ROS generation, produced by oxidative stress, activates hepatic stellate cells, increases the expression of pro-inflammatory cytokines such as tumor necrosis factor-alpha (TNF-α), interleukin-6 (IL-6), and interleukin-1 (IL-1), and triggers apoptosis and liver fibrosis." (PMID 40647324, 2025). "The higher NIC dose resulted in even more significant reductions in TNF-α and iNOS protein expression and NF-κB-p65 gene expression, with reductions of approximately 50%, 65%, and 50%, respectively, relative to the TAA-induced liver fibrosis group." (PMID 41365955, 2025). "Notably, betaine attenuated MIF effects in myocardial tissue reducing levels of MDA, AOPP, TNF, TGF-β1, PDGF-BB and increasing SOD and catalase activity in the coexistence of liver fibrosis." (PMID 41020850, 2025). "Liver tissues derived from the SGLT2-MOE-ASO group demonstrated increased expression of tumor necrosis factor (TNF)-α, transforming growth factor (TGF)-β1, and the murine monocyte-macrophage marker F4/80 with mild liver fibrosis when compared with those from the SGLT-2-SNA2-ASO group." (PMID 39850319, 2025). "Reduced glutathione may also play a role in modulating the immune response by lowering levels of inflammatory markers such as TNF-α, CRP, and IL-6, which are known to contribute to liver fibrosis and inflammation." (PMID 41281287, 2025).
liver fibrosis (continued). "Among these inflammatory cytokines, IL-6, TNF, and TGF-β are key pro-inflammatory and pro-fibrotic factors that maintain immune responses, tissue repair, and homeostasis, and activate hematopoietic stem cells and drive liver fibrosis." (PMID 40778202, 2025). "A recent study found that, in a mouse model of CCl4-induced liver fibrosis, the Citrus aurantium extract astragalin inhibited the expression of TNF-α, IL-18, and IL-1β mRNAs in the livers of fibrotic mice through the NF-κB/NLRP3 inflammasome pathway, significantly ameliorating liver fibrosis." (PMID 39995661, 2025). "The results showed that BMP could inhibit the proliferation of HSCs-T6 induced by LPS and decrease the levels of TGF-β1, IL-1β and TNF-α, indicating that BMP has a good effect on anti-hepatic fibrosis and relieving related inflammation." (PMID 38576476, 2024). "Additionally, MO Extract alleviated the inflammatory response by suppressing the TNF- α and MCP-1 and prevented hepatic fibrosis via Nrf2-mediated inhibition of the TGF-β1/Smad pathway." (PMID 38303002, 2024). "Meanwhile, ACN from Aronia melanocarpa Elliot could prevent liver fibrosis by inactivating α-SMA expression, reducing the expression of inflammatory factors such as TNF-α and IL-1 and inhibiting the TGF-β1 secretion and Collagen I deposition." (PMID 39512816, 2024). "In addition, sulforaphane can also decrease the levels of the inflammatory cytokines tumor necrosis factor-alpha (TNF-ɑ) and transforming growth factor-β (TGF-β) and inhibit hepatic fibrosis." (PMID 38164175, 2024). "IL-6, TNF, and IL-1-β may act synergistically with TGF-β, and the genetic deletion of these cytokines may reduce the development of liver fibrosis." (PMID 39063116, 2024). "By administering a specific dosage of FCD, the expression of inflammation-related genes such as NLRP3 and TNF-α was reduced to their usual levels, suggesting that FCD plays a role in impeding the conversion of stellate cells to fibroblasts and reducing liver fibrosis." (PMID 38790823, 2024). "In liver fibrosis models, such as those induced by dimethylnitrosamine (DMN), resveratrol reduces inflammatory cell infiltration and fibrosis, lowering MDA levels, increasing GPx and SOD levels, and inhibiting inflammatory mediators like NO, TNF-α, and IL-1β." (PMID 39273295, 2024). "Remarkably, the liver fibrosis mice treated with vitamin D resulted in a substantial reduction in the levels of the tested cytokines: IL-1β (2.2-fold), IL-4 (1.9-fold), IL-6 (8-fold), OPN (1.45-fold), and TNF-α (1.7-fold) compared to CCl4 alone." (PMID 39654627, 2024). "Olibanum extract has shown its hepatoprotective activity by inhibiting liver fibrosis and downregulating the expression of cytokines including transforming growth factor β (TGF-β), cyclooxygenase-2 (COX-2), and tumor necrosis factor-α (TNF-α)." (PMID 38674483, 2024). "Previous studies have shown that TNF-α is necessary for initiating NAFLD and its development into NASH by upregulating key molecules involved in inflammatory cytokines, lipid metabolism, and liver fibrosis." (PMID 38751599, 2024). "Furthermore, TNF-α can stimulate hepatic stellate cells, responsible for excessive extracellular matrix production and TGF-β activation, leading to liver fibrosis." (PMID 39458995, 2024). "TNF-α is essential for HSC stimulation and ECM production throughout liver fibrosis." (PMID 36826975, 2023). "In addition, the upregulated release of proinflammatory (TNF-α and IL-6) and profibrogenic (TGF-β) cytokines by Kupffer cells and stimulated HSCs is one of the first manifestations of liver fibrosis." (PMID 36978885, 2023). "The absence of a correlation between TNF-α levels and disease severity, represented by the degree of liver fibrosis, is also shown." (PMID 36820674, 2023).